AR (androgen receptor)
Diseases named in the same sentence as AR in open-access papers (continued):
Sharing a sentence is not in itself a finding about the gene and the disease.
prostate carcinoma (continued). "We explored whether the anti-prostate cancer (PC) activity of the androgen receptor-axis-targeted agents (ARATs) abiraterone and enzalutamide is enhanced by metformin." (PMID 33562646, 2021). "Therefore, understanding AR‐mediated tumorigenesis during prostate cancer progression is highly important for prostate cancer therapy." (PMID 33219721, 2021). "Our data suggest that BRG1 binding is associated with the expression of DNA replication genes in prostate cancer cells that is independent of AR and FOXA1." (PMID 33596994, 2021). "In this review, we examine whether a better understanding of how the activity of the target for the default first treatment, the androgen receptor, is regulated in prostate cancer tissues can improve prostate cancer treatment plans." (PMID 34439101, 2021). "The androgen receptor (AR) is critical in the progression of prostate cancer (PCa)." (PMID 34354111, 2021). "In addition, emerging anti-androgen drugs like enzalutamide, which specifically bind to the LBD of the AR, show highly promising effects in patients with castration-resistant prostate cancer." (PMID 34103477, 2021). "Furthermore, Pearson’s correlation analysis revealed that the expression of FAM64A was positively correlated with the expression of AR in prostate cancer (TCGA: P < 0.001, R = 0.864)." (PMID 34215720, 2021). "Therefore, the status of the AR should be considered when using FOXO3a agonists to inhibit prostate cancer." (PMID 34026624, 2021). "This dependence on AR makes localized prostate cancer highly sensitive to blockading AR signaling by drugs that target DHT production, such as LH-RH agonists, or CYP17A1 inhibitors, such as abiraterone acetate, or drugs directly inhibiting the AR such as enzalutamide, darolutamide, or apalutamide." (PMID 35004302, 2021). "Interestingly, in human prostate cancer cells, the NF-κB inhibitor, curcumin and its potent analog ca27, were shown to down-regulate AR expression via an oxidative stress mediated mechanism." (PMID 35582006, 2021). "The supplement of quercetin could decrease the expressions of AKT, AR, cell proliferative and anti-apoptotic proteins on prostate cancer in the in vivo model." (PMID 33500463, 2021). "6PGD is an androgen receptor (AR)-regulated gene and is elevated in prostate cancer." (PMID 34382934, 2021). "For example, the androgen receptor variant 7AR-V7 expression of CTCs had no prognostic value in patients with prostate cancer." (PMID 34271857, 2021). "AR-targeting miRNAs have been suggested as potent tumor suppressors in prostate cancer." (PMID 34831421, 2021). "ASC-J9 could also inhibit the proliferation and metastasis of prostate cancer by regulating pSTAT3-C-C motif chemokine-2 (CCL2) signal transduction through an AR-dependent pathway via inhibiting the expression of the protein inhibitor of STAT3 (PIAS3)." (PMID 34295247, 2021). "In addition, they can also affect the development of prostate cancer by regulating AR-dependent gene transcription." (PMID 35069596, 2021). "This AR/MAPK crosstalk is conserved across multiple cell lines including in prostate cancer." (PMID 33923536, 2021). "However, HOXB13 is associated with various renal carcinoma targets involved in the Wnt pathway but combined with the introduction of HOXB13 through the Wnt signal pathway and the androgen receptor signal pathway to inhibit the growth of prostate cancer cells." (PMID 34306077, 2021). "AR plays a crucial role in prostate cancer growth and development." (PMID 33809749, 2021). "Endocrine therapies for prostate cancer inhibit the androgen receptor (AR) transcription factor." (PMID 34737261, 2021). "AR activity was inhibited by IL-10 in prostate cancer cells." (PMID 34204596, 2021).
prostate carcinoma (continued). "PROTAC-based AR degraders represent a novel approach for treating prostate cancer." (PMID 34488823, 2021). "In addition to the down expression of androgen receptor factors, curcumin has also shown its effects in xenografts and prostate cancer cell lines via minimizing the production of testosterone." (PMID 33807174, 2021). "Thus, androgens, particularly testosterone (T) and dihydrotestosterone (DHT), which serve as the major endogenous ligands of AR, are the key drivers for both the initiation and progression of prostate cancer." (PMID 33750894, 2021). "Thus, modulation of the androgen receptor axis via natural products contributes to prostate cancer therapy." (PMID 33807174, 2021). "Our finding that KLF5 and AR opposition converged on a set of genes that define basal cell identity, and that KLF5 overexpression in AR-positive prostate cancer cells enhanced expression of the basal cytokeratin CK5, highlights a role for KLF5 in supporting a mixed basal/luminal cell identity." (PMID 34737261, 2021). "As prostate cancer is dependent on androgen receptor (AR) pathway signaling for proliferation, relapse following androgen deprivation therapy relies on reactivation of the AR or crosstalk between the AR and other signal transduction pathways." (PMID 34298682, 2021). "Changes in the N-Myc cistrome, its interacting co-factors, and N-Myc-directed epigenomic reprogramming are androgen-dependent and drive a lineage switch in prostate cancer epithelial cells towards a neural identity that favors the development of AR independence and NEPC5–7." (PMID 34099734, 2021). "Findings from this study suggest that the inhibitor specifically targets KDM4B in late S-phase due to activation of PLK1 transcription via B-MYB, justifying the development of this KDM4B inhibitor for AR+ prostate cancer and opening up the possibility for new treatments in the AR+ subgroup of BC." (PMID 34778065, 2021). "From this perspective, some treatments under development may help to slow down the progression to AR-independent prostate cancers." (PMID 34071114, 2021). "MiR-let-7c-mediated inhibition of AR can reduce the proliferation of prostate cancer cells." (PMID 34831421, 2021). "Mechanistic evaluation in prostate cancer cell line models suggests that AR-mediated regulation of the pentose phosphate pathway occurs through upregulation of G6PD in response to mTOR,52 resulting in the production of nucleotide precursors for DNA synthesis and NADPH to sustain lipogenesis." (PMID 34262149, 2021). "In addition, darolutamide and its enantiomers and metabolites on AR dimerization have inhibitory activities in prostate cancer AR wild type, AR W742C mutant, and AR W742L mutant cell lines." (PMID 34976824, 2021). "Furthermore, as we have previously published, due to reciprocal feedback inhibition between the PI3K and AR pathways, combined inhibition of these pathways is required in prostate cancer." (PMID 34417459, 2021). "Prostate cancer is highly dependent on AR transcriptional activity." (PMID 33398037, 2021). "Additionally, decreased AR expression induced stemness phenotypes in prostate cancer cells through STAT3 activation." (PMID 34226586, 2021). "This analysis strategy revealed the Androgen Receptor (AR) as the top prostate cancer-specific gene hit, but the next four top-ranked hits were genes not previously associated with prostate cancer: KIF4A, MRPL13, NDUFB11, and TSR2 (top 5)." (PMID 34326322, 2021). "Moreover, this compound revealed the positive effect on prostate cancer by the inhibition of HIF-1α-mediated androgen receptor signaling and reducing proliferation of prostate cancer in vitro and in vivo." (PMID 34948455, 2021). "The androgen receptor (AR) is the driving force of prostate cancer growth." (PMID 34570813, 2021).
prostate carcinoma (continued). "We further examined NGF expression with signatures reflecting AR signaling components in TCGA prostate cancer dataset and found that tissues expressing low levels of the NGF were significantly associated with gene signatures of upregulated androgen responsiveness by a GSEA." (PMID 33398073, 2021). "Therefore, the PI3K/Akt pathway is an important potential target of non-AR pathway in the treatment of prostate cancer." (PMID 35342388, 2021). "AR alters the expression of its downstream genes by interacting with coregulators, including activators and repressors, thereby regulating the transcription of androgen response genes, which play a crucial role in prostate cancer metastasis." (PMID 34864817, 2021). "Prostate cancer (PCa) is dependent on the androgen receptor (AR)." (PMID 33446905, 2021). "Prostate cancer is largely driven by androgen receptor (AR) signaling activation." (PMID 34318630, 2021). "Given the dependency of AR and PI3K pathway signaling in Pten-deficient prostate cancer, we next investigated if the antitumor activity of apalutamide could be enhanced with AKT inhibition." (PMID 34439133, 2021). "Most prostate cancer cells have a luminal identity and remain dependent on AR activity." (PMID 34737261, 2021). "The androgen receptor inhibitor enzalutamide has demonstrated consistent benefits in men with prostate cancer at various stages of the disease, from hormone-sensitive prostate cancer (HSPC) to metastatic (m) and non-metastatic (nm) castration-resistant prostate cancer (CRPC)." (PMID 34884981, 2021). "This may be one of the reasons why sorafenib promoted the effects of an AR inhibitor in AR-dependent prostate cancer." (PMID 34026624, 2021). "AR-targeted drugs have been approved to treat prostate cancer only." (PMID 34392453, 2021). "Fused in Sarcoma (FUS) could function as an AR-interacting protein that enhances AR transcriptional activity in prostate cancer." (PMID 33391416, 2021). "Together, these data suggest that MAPK inhibition in combination with enzalutamide may be effective in AR-driven prostate cancer cells having an activated MAPK pathway, through an activating BRAF mutation." (PMID 34211036, 2021). "Interestingly, this effect was not only observed in prostate cancer cells but also in endocrine resistant (triple negative) breast cancer cells that express AR protein." (PMID 35582006, 2021). "In patients with prostatic cancer, it has been demonstrated that AR gene polysomy may lead to castration therapy resistance." (PMID 33534004, 2021). "Prostate cancer (PCa) lists as the second most lethal cancer for men in western countries, and androgen receptor (AR) plays a central role in its initiation and progression, which prompts the development of androgen deprivation therapy (ADT) as the standard treatment." (PMID 34692685, 2021). "However recent report on indirect activation of BCLX promoter via AR-> integrin α6->NFkB mechanism provided more nuanced interpretation of androgen-dependency of BCLX expression in prostate cancer cells." (PMID 33668112, 2021). "In prostate cancer, its overexpression is in part due to androgen receptor (AR) activity." (PMID 34725334, 2021). "These compounds inhibit AR signaling and tumor growth in prostate cancer." (PMID 34201346, 2021). "Androgens drive the growth of prostate cancer through androgen receptor (AR) signaling." (PMID 33671134, 2021).
prostate carcinoma (continued). "Taken together the findings of these different studies suggest the impact of taxanes on AR signalling may be dependent upon the concentrations used and/or the hormone-sensitivity of the prostate cancer cell model studied." (PMID 33572755, 2021). "The combination of NF-κB inhibition with AR inhibitor could be a promising target to prevent the evolution of prostate cancer." (PMID 33802402, 2021). "Taken together, these findings are in accord with studies that have consistently identified that CAMKK2 was overexpressed in human prostate tumor biopsies, highlighting the significance of AR-CAMKK2-AMPK signaling in mediating energy metabolism in prostate cancer." (PMID 32927797, 2020). "We employed a multitude of genomic approaches including Affymetrix splicing array, whole transcriptome RNA-seq analysis, and RT-PCR to show that AR signaling regulates the transcriptome of prostate cancer cells by modulating ASE of a wide array of genes involved in regulating protein function." (PMID 32820253, 2020). "AR and AKT are signaling pathways associated with EMT in prostate cancer." (PMID 32972001, 2020). "Finally, we investigated the functional significance of ERRα-mediated up-regulation of AKR1C3 in activation of AR signaling in prostate cancer cells." (PMID 32226548, 2020). "Androgen receptor (AR) is a crucial oncogenic factor in the development of prostate cancer." (PMID 32210733, 2020). "Notably, AR-repressed CRPC-Lnc #6 is markedly upregulated by androgen depletion in AR-positive prostate cancer cells." (PMID 32704143, 2020). "All prostate cancer samples displayed ERa expression on the apical pole of AR+ epithelium." (PMID 33266334, 2020). "The AR has been well characterized as a key driver for the growth of prostate cancer in men." (PMID 33062889, 2020). "Since KDM7A is known to regulate AR activity in prostate cancer cells, we speculated that it may control AR activity as an epigenetic regulator in bladder cancer cells." (PMID 32781788, 2020). "Importantly, next‐generation sequencing has suggested HNRNPL as a key regulator of prostate cancer via modulating the alternative splicing of multiple RNAs such as the core oncogene androgen receptor." (PMID 32915499, 2020). "To verify our hypothesis, we next examined the expression profiles of key steroidogenic enzymes involved in androgen biosynthesis in AR-positive prostate cancer cells with either stable ERRα- overexpression or -knockdown." (PMID 32226548, 2020). "Although it has not been studied in OSCC, the increase in levels of chymase has been shown to influence prostate cancer progression via downregulation of expression of signals for the androgen receptor expressed in prostate cancer cells thereby increasing the invasive ability of these cells." (PMID 35047982, 2020). "Interestingly, alternative splicing of AR in prostate cancer is suggested to be important for acquiring the endocrine therapy resistance, as described in a later part." (PMID 32106418, 2020). "CAMKK2 is upregulated in prostate cancer directly through the androgen receptor." (PMID 31941153, 2020). "Therefore, the primary course of treatment for metastatic prostate cancer is to inhibit AR transcriptional activity by using a combination of competitive AR antagonists and drugs that block androgen production." (PMID 32296610, 2020). "In this study, we leveraged a combination of next-generation sequencing and molecular methodologies to provide critical pieces of evidence for a direct role of AR and its clinical inhibitors in regulating the transcriptome of prostate cancer cells by modulating global alternative splicing." (PMID 32820253, 2020). "Therefore, the global comparison of ASE between the pharmacological inhibitor and genomic inhibition of AR signaling in prostate cancer cell lines needs further validation." (PMID 32820253, 2020). "JMJD1A regulates the transcriptional program of the androgen receptor in prostate cancer cells." (PMID 32461996, 2020).
prostate carcinoma (continued). "AR is essential for the initiation and progression of prostate cancer." (PMID 32296610, 2020). "Because MYC and AR signaling are essential for prostate cancer initiation, MYC may be another key determinant both of BET bromodomain inhibitor and LSD1 inhibitor sensitivity in PCa." (PMID 31901895, 2020). "A similar approach has been used in prostate cancer, where constitutively active androgen receptor variants lacking the ligand binding domain arise from the use of an intronic PAS." (PMID 32560344, 2020). "Among the many functions, FLNA interacts with AR reducing its activation in prostate cancer." (PMID 32626651, 2020). "Our group and others have previously shown that genistein combined polysaccharide (GCP), an aglycone isoflavone-rich extract with high bioavailability and low toxicity, can inhibit prostate cancer (CaP) cell growth and survival as well as androgen receptor (AR) activity." (PMID 32796613, 2020). "In further confirmation of this hypothesis, the same experiment was repeated with an additional pretreatment step using the chemotherapeutic agent bicalutamide, an AR competitive inhibitor approved for prostate cancer therapy under the trade name Casodex." (PMID 33207735, 2020). "Western blot analysis of important signaling molecules involved in prostate cancer demonstrated that the AR protein expression was significantly reduced by arctigenin treatment compared to HF control, along with a significantly increased protein expression of Nkx3.1." (PMID 31996731, 2020). "Asim and colleagues could show that LCoR inhibits prostate cancer growth in a xenograft mouse model via co-repression of activated androgen receptor (AR)." (PMID 32157438, 2020). "Intriguingly, AR signaling, the most commonly targeted and mutated molecular signature in metastatic castration–resistant prostate cancer, was not captured by a CENPA-focused analysis, a finding that we further confirmed in tissue culture experiments." (PMID 32371391, 2020). "AR inhibitors are already approved in the clinic for treatment of prostate cancer and are under investigation in COVID-19 patients; BET inhibitors are also in clinical development for other indications and could be rapidly repurposed for COVID-19." (PMID 33310900, 2020). "T60 also inhibits androgen receptor activity and prostate cancer cell growth." (PMID 33598437, 2020). "The most well-known and -studied androgen/AR-dependent cancer is prostate cancer." (PMID 32714315, 2020). "Additionally, the compound inhibited AR-signaling and resensitized AR-V7-positive prostate cancer cells to enzalutamide, presumably due to AR-V7 inhibition." (PMID 33271756, 2020). "The role of androgen receptor (AR) activation and expression is well understood in prostate cancer." (PMID 33062889, 2020). "Indeed, epigenetic processes which control AR activity have been reported to play a role in prostate cancer development." (PMID 32781788, 2020). "When the lysine residues were substituted by arginine, which mimics a non-acetylated phenotype of the AR, the mutated AR proteins were mainly localized in the cytoplasm despite androgen stimulus in the androgen-dependent LNCaP prostate cancer cells." (PMID 32927797, 2020). "These important findings could lead to new therapeutic strategies combining effective AR targeted therapies with lipid synthesis inhibitors for the treatment of advanced prostate cancer." (PMID 33187317, 2020). "Indeed, the growth and maintenance of prostate tissue depends on the androgens produced by the testes and adrenal glands, and intracellular androgen receptor (AR) signaling plays an important role in the formation and development of prostate cancers." (PMID 32760737, 2020).